NAMPT (nicotinamide phosphoribosyltransferase)
Diseases named in the same sentence as NAMPT in open-access papers (continued):
Sharing a sentence is not in itself a finding about the gene and the disease.
tumor (continued). "For example, nicotinamide phosphoribosyltransferase (NAMPT)-mediated NAD+ metabolism enhanced interferon gamma-induced programmed cell death 1 ligand 1 (PD-L1) expression and drove tumor immune evasion in a CD8+ T cell-dependent manner." (PMID 36845744, 2023). "In both cell lines, the coadministration of NAMPT and NAPRT inhibitors cooperated inhibiting tumor growth." (PMID 36864434, 2023). "We further showed that the combination of NAMPT inhibitor FK866, a potential tumor therapy agent, with high-dose NMN local treatment increased the efficacy of tumor suppression in vitro and in vivo." (PMID 37173894, 2023). "In conclusion, the coinhibition of NAMPT and NAPRT improved the efficacy of antitumor treatment, indicating that the reduction in the NAD pool is important to prevent tumor growth." (PMID 36864434, 2023). "We observed that NAMPT downregulation reduced the tumorigenic and CSC-like properties of tumor cells in our cell lines." (PMID 36864434, 2023). "In CSCs, NAMPT regulates epithelial-mesenchymal transition (EMT) and tumor dedifferentiation/reprograming via controlling cellular functions that promote proliferation and pathways mediated by SIRT1 and PARP1." (PMID 36819783, 2023). "Nicotinamide phosphoribosyltransferase (NAMPT), a rate-limiting enzyme involved in NAD+ biosynthesis, protects tumor cells from glucose deprivation-induced oxidative stress by maintaining NADPH levels." (PMID 38020920, 2023). "Several potent and selective NAMPT inhibitors have been developed (e.g., FK866 and CHS-828), which exhibit strong anti-tumor activity in in vitro and in vivo tumor models by efficiently lowering NAD production in a dose- and time-dependent manner." (PMID 37259338, 2023). "Ligand–receptor pairs, such as PROS1-AXL, NAMPT-INSR, MDK-LRP1, MDK-ALK, GAS6-MERTK, and GAS6-AXL, between endothelial and tumor cells exhibited a higher communication possibility than that between endothelial cells and thyrocytes." (PMID 37733241, 2023). "The synergistic combination of NAMPT and PARP inhibition increased the inhibitory effect on tumor cells." (PMID 38116009, 2023). "As a kind of small-molecule NAMPT inhibitor, FK866 has shown anticancer activity in several tumor models by depleting NAD levels." (PMID 35515130, 2022). "SIRT1 increases MYC transcriptional activity through deacetylation, which in turn increases NAD+ through increased expression of NAMPT, thereby enhancing SIRT1 activity, and this positive feedback inhibits tumor cell senescence and apoptosis." (PMID 36523971, 2022). "It is an inhibitor of nicotinamide-recycling enzyme (NAMPT/PBEF) that catalyzes the rate-limiting step of NAD+ synthesis, resulting in apoptosis induction in a tumor due to NAD+ depletion." (PMID 36139711, 2022). "Later, it was observed that KPT-9274 was also capable of inhibiting NAMPT, which is why it has been proposed as a candidate drug in tumours that express high levels of PAK4 and NAMPT." (PMID 36078035, 2022). "Previous studies found that high protein levels of NAPRT conferred resistance to NAMPT inhibition in several tumor types whereas the simultaneous blockade of NAMPT and NAPRT results in marked anti-tumor effects." (PMID 35890155, 2022). "The NAMPT inhibitor, FK866, has shown anticancer activity in several tumor models and has been tested in clinical trials." (PMID 35515130, 2022). "Here we show that tumor environment enriched in vitamin B3 (NAM) or nicotinic acid (NA) significantly lowers the anti-tumor efficacy of APO866, a prototypic NAMPT inhibitor." (PMID 35396381, 2022). "The existence of Paneth‐like cells in GC was further confirmed in the primary tumour sections by RNAscope with the marker genes LYZ and NAMPT." (PMID 35184420, 2022). "The result shows that NAM-enriched diet cannot fully abrogate APO866 anti-tumor effect when microbiota is depleted, hampering any conversion of NAM to NA to bypass NAMPT inhibition in tumors." (PMID 35396381, 2022).
tumor (continued). "NAMPT activates several transcription factors involved in EMT, such as SNAI1, TWIST and FOXC2, favouring tumour invasion and metastasis." (PMID 36078035, 2022). "BID, NAMPT, and BIRC5 were detected with the same results in tumor tissues and with adjacent normal kidney tissues, while CANX was not significantly different." (PMID 34988121, 2021). "Metabolic reprogramming of macrophages has been appreciated as an important factor for effective immune responses, including those that combat tumor growth, and our findings indicate that IFN/STAT1-induced NAMPT is a key component of this response." (PMID 33976173, 2021). "We reported that NAMPT transcription and eNAMPT secretion are highly upregulated by hypoxia via HIF-2α signaling and tumor-relevant growth factors." (PMID 34959723, 2021). "NAMPT has been described as a potent oncogene able to promote cell proliferation by increasing the NAD+ pool, leading to increased tumor progression and development." (PMID 33384409, 2021). "Through a screening in TCGA-KIRC database, we compared the expression levels of CANX, MAPK1, BIRC5, NAMPT, and BID in normal kidney tissues and renal clear cell tumor tissues, and we found that their expression levels in tumor tissues were upregulated." (PMID 34988121, 2021). "By inhibiting NAMPT, a key enzyme in NAD+ biosynthesis, reducing NAD+ levels can significantly inhibit tumor growth and improve patient survival." (PMID 33562281, 2021). "Tumor cells support their requirement for increased NAD pools by overexpressing NAD salvage pathway enzymes, like NAMPT." (PMID 32459815, 2020). "In fact, FK866 was developed to block growth of tumor cells that can be highly dependent on NAM- and NAMPT-controlled NAD biosynthesis." (PMID 32459815, 2020). "Conversely, nicotinamide phosphoribosyl transferase (NAMPT; which is a key enzyme in the production of NAD+ via the alternative salvage pathway) was upregulated in most tumour samples." (PMID 32390008, 2020). "The levels of NAD+ and its metabolites are critical for tumor cell proliferation; therefore, the effects of the fused isoselenazolium salts on the NMN, NAD+ and NADH levels as well as NAMPT activity were tested." (PMID 33299068, 2020). "We demonstrate that dual inhibition of PAK4 and NAMPT can block PNET proliferation in vitro and arrest tumor growth in mouse models." (PMID 31795447, 2019). "NAMPT is markedly overexpressed in HGG and GBM tumors, correlating with tumor grade and able to predict patients' prognosis." (PMID 31119097, 2019). "In some cases, NAMPT was found to be a direct transcriptional target of c-Myc, resulting in a positive feedback loop between c-Myc, NAMPT, and SIRT1 that drove tumor cell proliferation and progression." (PMID 32010616, 2019). "Strikingly, and counterintuitively to the anti-tumor activity of DIO1, restoration of DIO1 expression resulted in moderate increase of TKT, NAMPT and IDH2 protein levels." (PMID 29272308, 2017). "In the case of the tumor cells used for this study, NAMPT and NRK seem to play a major role in NAD+ biosynthesis, as the simultaneous inhibition of NAMPT and CD73 significantly decreased intracellular NMN and NAD+ concentration." (PMID 26658104, 2016). "As the rate-limiting enzyme in primary salvage pathway, NAMPT expression level can greatly influence NAD metabolism and NAD dependent cellular processes in tumor cells." (PMID 27661117, 2016). "Accordingly, inhibitors of nicotinamide phosphoribosyltransferase (NamPT), the enzyme that catalyses the rate-limiting step in NAD+ biosynthesis, have been shown to possess moderate anti-tumour activity in monotherapy both in vitro and in vivo." (PMID 27754384, 2016). "Overall, we demonstrate that NAMPT and NAPRT are ubiquitously expressed in normal human tissues, and we have detected novel NAPRT transcripts, in normal tissues and in tumor cell lines." (PMID 26675378, 2016).
tumor (continued). "Nicotinamide phosphoribosyltransferase (NAMPT) inhibitors (e.g., FK866) target the most active pathway of NAD+ synthesis in tumor cells, but lack tumor-selectivity for use as a single agent." (PMID 25590809, 2015). "We used a catalytic inhibitor of NAMPT, FK866, which was shown to deplete energy reserve in metabolically active tumor cells and induce tumor cell death, to treat the isolated tumor cells from solid tumor nodes." (PMID 24279986, 2013). "Inhibition of NAMPT by FK866 suppressed the growth of isolated tumor cells from both Tg and KO-Tg mice and the formation of tumor spheres from single tumor cells, an indicator of the presence of cells with the ability to expand and repopulate tumors." (PMID 24279986, 2013). "However, in human hepatocellular carcinoma tissues, NAMPT expression and NAD+ levels were significantly downregulated in tumor-infiltrating NK cells, correlating negatively with patient survival." (PMID 40775221, 2025). "NAMPT‐mediated NAD+ biosynthesis induces H3K27 deacetylation, promoting tumor immune evasion This discovery unveils a metabolic‐epigenetic pathway governing PD‐L1 regulation and proposes potential therapeutic interventions to enhance the efficacy of immunotherapy in CC." (PMID 39988985, 2025). "Consequently, NAMPT inhibition induces cell death in vitro and suppresses ALK + ALCL tumor growth in vivo." (PMID 40775221, 2025). "Additionally, strong communication was observed between neutrophils and endothelial cells, specifically through the NAMPT-INSR interaction, a key signaling axis in tumor vascularization." (PMID 41208994, 2025). "The treatment by PF403 did not result in a reduction of NAMPT knockdown tumor volume, which was 21.16 ± 11.28 and 24.05 ± 13.99 mm3 in the vehicle group and treatment group, respectively." (PMID 40486861, 2025). "NAMPT exists in both extracellular (eNAMPT) and intracellular (iNAMPT) forms, with eNAMPT boosting TLR4-independent macrophages activation, and iNAMPT mediating NK mitochondrial homeostasis, suggesting anti-tumor cytoxicity." (PMID 40087771, 2025). "Moreover, we identified a previously unrecognized anti-tumor mechanism whereby disulfiram, an aldehyde dehydrogenase (ALDH) inhibitor, synergistically inhibited mitochondrial function when combined with NAMPT inhibitors - leading to cell cycle arrest in G2/M." (PMID 40280967, 2025). "If Carba1 or its analogs are used to prevent CIPN in the future, then it is essential to confirm that NAMPT stimulation does not promote tumor growth or compromise the anticancer efficacy of chemotherapy agents." (PMID 41160692, 2025). "Thus therapeutic inhibition of NAMPT with FK866 or SIRT1 with EX527 led to significant reduction of tumor angiogenesis and suppressed tumor growth." (PMID 40050933, 2025). "The interactions where non-tumor cells influenced tumor cells included NAMPT → INSR, MIF → CD74 and CXCR4, GRN → SORT1, and CD99 → CD99." (PMID 39095793, 2024). "Nicotinamide phosphoribosyltransferase (NAMPT) was necessary for the activation of T cells, and supplementation with NAD(+) could augment the tumor‐killing effect of T cells in CAR‐T and ICI treatment by rescuing TUB‐mediated NAMPT transcription in T cells." (PMID 38783893, 2024). "NAMPT and NAD+ not only affect tumor metabolism but also affect the tumor immune microenvironment." (PMID 38448544, 2024). "In these clinical studies, NAMPT inhibitors showed marginal or no tumor responses as well as side effects such as thrombocytopenia and lymphopenia (in the case of FK866) or gastrointestinal side effects (in the case of the orally administered CHS-828)." (PMID 38396769, 2024). "Expression of NAMPT, NAPRT, NT5E and QPRT were quantified by qPCR and Western blot in both established and primary GBM cell lines, and IHC was performed on sections from GBM tumours for the same proteins." (PMID 38893173, 2024).
tumor (continued). "However, NMRGs with significant AUC values (ENPP1, ENPP2, NAMPT, SIRT1, PARP1, NMNAT1, and PNP) were differentially expressed among tumor grades." (PMID 38254798, 2024). "Nicotinamide phosphoribosyltransferase (NAMPT), the rate-limiting enzyme in NAD+ biosynthesis, is a key enzyme in cell metabolism that influences the activity of NAD+-dependent enzymes to regulate tumor metabolism." (PMID 38448544, 2024). "Further investigation of the NAMPT enhancer #3 deletion locus via TOBIAS footprinting analysis revealed the enhanced enrichment of AP-1 TF binding in TWEAK-activated TNBC cell lines and Fn14-high TNBC tumours." (PMID 38965263, 2024). "Similarly, the NAMPT-degrading PROTAC A7 depleted intracellular NAMPT, reduced the levels of secreted NAMPT, and elicited remarkable antitumor responses in mouse tumor models." (PMID 38396769, 2024). "Thus, NAMPT, which has an important role in regulating NAD+ and ATP synthesis, should also have a role in regulating immunity in the tumor microenvironment." (PMID 35776198, 2023). "Mechanistically, NAMPT may modulate SIRT1 and PARP1 activity to regulate stem cell signaling pathways, thus influencing the EMT and tumor cell dedifferentiation." (PMID 38116009, 2023). "Finally, the inhibition of both NAMPT and NAPRT improved the efficiency of the treatment, indicating that the reduction of the NAD pool is important for preventing tumor growth." (PMID 36864434, 2023). "Moreover, the inhibition of NAMPT through treatment with the visfatin inhibitor FK866 significantly decreased stemness expression and reduced tumor size." (PMID 36830834, 2023). "High levels of NAMPT expression and the NAD+/NADH ratio may contribute to tumor growth or pathological degeneration." (PMID 36797299, 2023). "They found that NAMPT inhibited the tumorigenesis of neutrophils by inhibiting SIRT-1 signal transduction and then blocked the transcription of angiogenic genes to play an anti-tumor role." (PMID 35906622, 2022). "We elected to use STF-118804 for our in-vivo experimentation as it showed promising results as a NAMPT-specific inhibitor in-vitro, has not been explored as thoroughly in the literature, and has been shown to sensitize tumor cells to chemotherapeutic agents." (PMID 35814452, 2022). "Our analysis results showed that NAMPT has a high expression trend in the patients with a high MYC expression group, and compared with adjacent tissues, NAMPT has a significant upregulation trend in patient tumor tissues." (PMID 33540574, 2021). "As 3D cultured cells are often more representative of the in vivo situation compared to 2D cultured cells, multi-cellular tumor spheroids (MCTS) of the OS cell lines MHM, MG63, SAOS2 were generated and treated for 72 h with the NAMPT inhibitor FK866 to determine cell viability." (PMID 34200964, 2021). "While a specific receptor for visfatin has not yet been identified, its tumor-promoting effects are dependent on NAMPT enzymatic activity or mediated via transactivation of signaling pathways, such as the PI3K/Akt, MAPK, and STAT3 signaling pathways." (PMID 33535537, 2021). "NAMPT, a critical NAD+ synthesis enzyme, is found up-regulated in many solid tumors supporting tumor cells for their high demand of NAD+, which makes it a prognosis index for tumor malignancy or progression." (PMID 34366891, 2021). "In addition, we have shown that NAMPT transcription and eNAMPT secretion are potently stimulated by hypoxia in an HIF-2α-dependent manner, potentially influencing the PCa tumor microenvironment." (PMID 34959723, 2021). "In addition, the response of CANX, BID, NAMPT, and BIRC5 with different expression levels to immune checkpoint inhibitors was predicted based on Tumor Immune Dysfunction and Exclusion (TIDE) algorithm." (PMID 34988121, 2021).
tumor (continued). "NAMPT has been widely explored as a target for tumor chemotherapy, and the inhibitor FK866 and other NAMPT-targeting drugs have been subjects of clinical trials, with the rationale of inhibiting NAD-dependent Warburg aerobic glycolysis of tumor cells." (PMID 33976173, 2021). "These pathway correlations support the hypothesis that NAMPT modulates SIRT1 and PARP1 to control the cellular functions that promote proliferation and stemness pathways, thus regulating the EMT and tumor dedifferentiation." (PMID 33384409, 2021). "All this leads to the observation that the effect of NAMPT inhibitors on tumor growth and metastasis formation is largely independent of an effect on the tumors but is mediated by an effect on the microenvironment." (PMID 32477131, 2020). "NAMPT over-expression in vivo increased tumor formation capability in both M14 and A375 cell lines (light blue line + DOX vs. black line-DOX), as highlighted following tumor growth kinetics over 4–5 weeks and analyzing tumor masses." (PMID 33419372, 2020). "On the other hand, CRISPR/Cas9 full knock-out NAMPT BRAFi-resistant MM cells are not viable, while inducible partial silencing drastically reduces tumor growth and aggressiveness." (PMID 33419372, 2020). "More recently, however, it has been shown that NAMPT inhibitors do not solely target the tumor but also have an effect on the immune system." (PMID 32477131, 2020). "Conversely, NAMPT expression was absent from clear cell tumour cells in two cases but positive in five (from weak to strong) with focal positivity seen in a further four cases." (PMID 32390008, 2020). "It is, therefore, not surprising that NAMPT is over expressed by tumoral cells, which take advantage from this to sustain growth rate and tumor progression." (PMID 32477131, 2020). "The knockdown of nicotinamide phosphoribosyltransferase (NAMPT), the gene involved in metabolic pathways and known to be upregulated in drug‐resistant tumor cells, was shown to increase the apoptosis of cisplatin‐resistant A549 cells following cisplatin treatment." (PMID 31025554, 2019). "Collectively, these findings suggest that NAMPT-targeting tumor therapy does not benefit patients as expected, and the clarification of the complicated tumor metabolism is necessary for the clinical development of drugs targeting the tumor metabolism." (PMID 31123329, 2019). "Moreover, FK866, a compound which inhibits nicotinamide-recycling enzyme NAMPT/PBEF, which is the bottleneck for NAD biosynthesis, resulted in anticancer effect as a tumor apoptosis inducer due to NAD+ depletion." (PMID 31687086, 2019). "Successful implementation of the strategy to widen the therapeutic index of NAMPT inhibitors by co-administration with niacin, will depend on the ability to correctly detect functional NAPRT in tumor tissue and on the ability of normal tissue to be protected by niacin administration." (PMID 29100430, 2017). "Thus, inhibition of NAMPT by small-molecule chemical compounds such as FK866, CHS828, and STF-118804 has emerged to be a promising therapeutic strategy for tumor treatment." (PMID 28097126, 2016). "Since NAMPT expression level and sensitivity to FK866 correlate, we hypothesized that tumoral cells with a high metabolism, i.e consuming or producing more metabolites with higher levels of NAMPT, would die at a faster rate than metabolically neutral cells." (PMID 27462772, 2016). "NAMPT, nicotinamide phosphoribosyltransferase, which converts nicotinamide (NAM) to nicotinamide mononucleotide (NMN), the immediate precursor of NAD, is an attractive therapeutic target as inhibition of NAMPT reduces cellular NAD levels and inhibits tumor growth in vivo." (PMID 27711204, 2016). "NAMPT inhibitors, including FK866 and CHS828, have potent anticancer activity in several preclinical models of solid and hematologic cancers by depleting NAD+ and ATP levels and thereby leading to tumor growth inhibition." (PMID 26658104, 2016).